PPARD (peroxisome proliferator activated receptor delta)
Diseases named in the same sentence as PPARD in open-access papers (continued):
Sharing a sentence is not in itself a finding about the gene and the disease.
asthma (3 papers, 2013 to 2023). "Together, the current data highlight the potential and benefits of PPARδ agonists to reduce the FMT potential, which is relevant for the clinical limitation of airway remodeling associated with asthma." (PMID 37175437, 2023). "However, little is known about the involvement of another type of peroxisome proliferator-activated receptor, PPARδ, in fibrosis-related processes, especially in asthma subepithelial fibrosis." (PMID 37175437, 2023). "Therefore, in this study, we investigated the effect of the PPARδ agonist GW501516 and the PPARδ antagonist GSK0660 administered alone or in combination on the phenotypic plasticity of HBF populations during TGF-β-induced subepithelial fibrosis in asthma." (PMID 37175437, 2023).
Cachexia (3 papers, 2011 to 2025). Severe weight loss, wasting of muscle, loss of appetite, and general debility related to a chronic disease. "PPARδ agonists have been linked to muscle atrophy, and one potential cause is the increased oxidation of amino acids, producing cachexia through increased protein turnover." (PMID 21843327, 2011). "LIF–STAT3 signaling suppresses PPARα to cause lipid imbalance, while fenofibrate restores lipid homeostasis and reduces cachexia, and PPARδ activation enhances oxidative metabolism and muscle endurance." (PMID 41476922, 2025). "Interestingly, the downregulated genes in muscle ECs of B16F10-cachexia mice were enriched for multiple cofactors of the transcriptional coactivator peroxisome proliferator-activated receptor (PPAR)γ coactivator 1α (PGC1α), such as Nrf1, PPARδ, Mef2, Hnf4 and forkhead box O1 (FOXO1)." (PMID 40419762, 2025).
cervical cancer (3 papers, 2021 to 2025). A primary or metastatic malignant neoplasm involving the cervix. "Specifically, APS inhibits the cisplatin resistance pathway and regulates the cell cycle by suppressing the Wnt/β-catenin pathway via the PPARD/CDC20 axis; APS also influences autophagy and upregulates γH2AX expression, thereby enhancing cervical cancer sensitivity to radiotherapy." (PMID 41306775, 2025).
cholesteatoma (3 papers, 2022 to 2024). A pathologic process characterized by the proliferation of keratinizing squamous epithelium resulting in the accumulation of keratin and cells in the middle ear and/or mastoid. "Another study also revealed that PPARδ/PDK1/PTEN/AKT/GSK3β/Cyclin D1 pathway was involved in the proliferation of keratinocytes in cholesteatoma." (PMID 35151320, 2022).
chronic kidney disease (3 papers, 2013 to 2022). Impairment of the renal function secondary to chronic kidney damage persisting for three or more months. "Polymorphisms in PPARD is significantly associated with the risk for chronic kidney disease in Japanese." (PMID 29514661, 2018).
cognitive decline (3 papers, 2017 to 2024). "In this study, we provide the first evidence for protective effects of 5a-mediated PPARδ activation against cognitive decline accompanied by neuroinflammation." (PMID 39431021, 2024). "Telmisartan as a unique ARB with a partial PPARδ agonistic property; has been shown to be neuroprotective and improve cognitive decline by reducing the levels of interleukin and TNF-α41–43." (PMID 29070884, 2017).
dermatitis (3 papers, 2013 to 2023). An inflammatory process affecting the skin. "Moreover, signaling via PPARδ-mediated pathways, mostly through Fabp5 upregulation, was mainly enhanced in allergen-induced dermatitis." (PMID 23977003, 2013). "Interestingly, in our mouse model of allergen-induced dermatitis we observed an increased expression of several of the investigated target genes involved in PPARδ signaling pathways in skin." (PMID 23977003, 2013). "Moreover, activation of both RAR and PPARδ was shown to alter skin inflammation." (PMID 23977003, 2013). "Thus, our findings suggest that ATRA levels, RAR-mediated signaling and signaling involved in PPARδ pathways are mainly increased in allergen-induced dermatitis and may contribute to the development and/or maintenance of allergic skin diseases." (PMID 23977003, 2013). "Furthermore, the increased ratio of Fabp5 vs. Crabp2 may indicate an up-regulation of the PPARδ pathway in allergen-induced dermatitis in addition to the altered RAR signaling." (PMID 23977003, 2013).
gastric tumors (3 papers, 2010 to 2023). "PPARδ dysregulation of Ccl20/Ccr6 axis promotes GAC carcinogenesis by remodeling gastric tumor microenvironment." (PMID 37572185, 2023). "Investigators found that PPARD expression was higher in human rectal and gastric tumors than in adjacent normal mucosa." (PMID 35163565, 2022). "Recently, we found that a newly generated villin-PPARD mouse model, in which PPARD is overexpressed in villin-positive gastric progenitor cells, demonstrated spontaneous development of large, invasive gastric tumors as the mice aged." (PMID 35163565, 2022). "Mice maintained on a diet supplemented with PPARδ agonist GW501516 following carcinogen administration resulted in the rapid development of gastric tumors in 12/15 animals, whereas treatment with either GW501516 or DMBA alone was not tumorigenic." (PMID 21318167, 2010). "In the present study, we describe a new gastric tumor mouse model that is dependent on the potent and highly selective PPARδ agonist GW501516 following carcinogen administration." (PMID 21318167, 2010). "PPARδ is ubiquitously expressed in gastrointestinal tissue and gastric tumors, and GW501516 elicited increased PPARδ nuclear staining and elevated pAkt in gastric epithelium and tumors." (PMID 21318167, 2010). "Gene ontology analysis of gene expression in the gastric tumors indicates that PPARδ, MMP12, MMP13, Cxcl1, Cxcl5, S100A8, and S100A9 share both common and disparate pathway interactions that likely contributed to the tumorigenic phenotype." (PMID 21318167, 2010). "PPARδ promotes gastric tumor stemness, inflammation, and GC tumorigenesis." (PMID 37572185, 2023). "Here we demonstrate that activation of PPARδ by a selective agonist, GW501516, rapidly induces highly metastatic gastric tumors following carcinogen administration, which expressed a markedly increased inflammatory gene expression signature." (PMID 21318167, 2010). "The increased expression of the PPARδ target gene, Agptl4, the TGFβ-activated genes Runx1 and Runx2, and S100A8 and S100A9 in the gastric tumors indeed suggests a duality of function of both PPARδ and TGFβ signaling in gastric tumorigenesis." (PMID 21318167, 2010).
glioblastoma (3 papers, 2021 to 2025). The most malignant astrocytic tumor (WHO grade IV). "This CDK12/GSK3β/PPARD axis was required for glioblastoma cell proliferation and metabolic homeostasis." (PMID 40996961, 2025).
Impaired glucose tolerance (3 papers, 2013 to 2022). An abnormal resistance to glucose, i.e., a reduction in the ability to maintain glucose levels in the blood stream within normal limits following oral or intravenous administration of glucose. "A genetic polymorphism in PPARD (rs 2267668; A/G intron variant) affects insulin sensitivity by modifying skeletal muscle glucose uptake and also predicts the conversion from impaired glucose tolerance to T2DM." (PMID 35205333, 2022). "Genetic polymorphism in PPARD (rs2267668; A/G: PPARD-2) has also been described to affect insulin sensitivity and the conversion from impaired glucose tolerance to T2DM." (PMID 35205333, 2022).
intestinal polyp (3 papers, 2006 to 2008). Discrete abnormal tissue masses that protrude into the lumen of the intestine. "In contrast, activation of PPARδ using a synthetic ligand increases the number and size of intestinal polyps; indeed, PPARδ-deficient CRC cells can establish tumours when grown as xenografts in nude mice." (PMID 16969348, 2006). "Loss of PPARδdid not significantly change the median size of intestinal polyps, althoughpolyps > 1 mm were decreased upon PPARδ dosage reduction, which was further pronounced for polyps > 2 mm." (PMID 18528523, 2008).
invasive breast carcinoma (3 papers, 2016 to 2023). A carcinoma that infiltrates the breast parenchyma. "From a clinical perspective, this result is concordant with the increased expression of PPARδ in invasive breast cancer and by manifestation of a PPARδ signaling network that predicts poor survival in this disease." (PMID 28077942, 2016).
muscular dystrophies (3 papers, 2011 to 2023). "Our study and other recent work underline the high potential of pharmacological activators of AMPK and PPARδ as part of rational drug treatments for muscular dystrophies." (PMID 22908954, 2012).
Nephropathy (3 papers, 2011 to 2020). A nonspecific term referring to disease or damage of the kidneys. "Thus, we examined the renoprotective effect of GW501516, a PPARδ agonist, in a protein-overload mouse nephropathy model and identified its molecular mechanism." (PMID 21966476, 2011).
osteosarcoma (3 papers, 2020 to 2024). A usually aggressive malignant bone-forming mesenchymal neoplasm, predominantly affecting adolescents and young adults. "Because PPARD has the highest risk coefficient in uni-Cox analysis, it was selected for experimental verification in osteosarcoma." (PMID 38212774, 2024). "We found that PPARD was highly expressed in osteosarcoma cell lines, and the highest expression was found in MG-63 and Saos-2 cells." (PMID 38212774, 2024). "What is more, we verified the expression of PPARD in osteosarcoma and its function at the cellular level." (PMID 38212774, 2024). "We first evaluated the protein expression profiles of PPARD in osteosarcoma cell lines and osteoblast." (PMID 38212774, 2024). "It was shown that only PPARδ gene knockdown inhibits 20 dynes/cm2 shear force-induced SCD-1 protein expression in human MG63 osteosarcoma cells." (PMID 32630668, 2020). "We found that 20, but not 2, dynes/cm2 shear force surprisingly increases the SCD-1 levels in human MG63 osteosarcoma cells through the activation of Smad1/5 signaling and PPARδ transcriptional factor." (PMID 32630668, 2020). "Smad1 or Smad5 gene knockdown in human MG63 osteosarcoma cells also blocked the PPARδ transcription activation." (PMID 32630668, 2020). "Smad1 or Smad5 gene knockdown in MG63 osteosarcoma cells blocked the PPARδ protein expression of 20 dynes/cm2 shear force induction." (PMID 32630668, 2020). "Finally, we verified that PPARD played a role as a carcinogen in osteosarcoma, which provided a direction for targeted treatment of osteosarcoma in the future." (PMID 38212774, 2024). "By using the PPARδ transcription factor enzyme-linked immunosorbent assay (ELISA), as expected, 20 dynes/cm2 shear force significantly increased PPARδ transcription activity in a time-dependent manner in human MG63 osteosarcoma cells compared to the untreated controls." (PMID 32630668, 2020). "Combined with these studies, we suggested that transcription regulation of SCD-1 is also in a context-dependent manner and PPARδ could be another transcription mediator in osteosarcoma cells under high shear force stimulation." (PMID 32630668, 2020). "Moreover, interesting results showed that cells transfected with PPARδ- or SCD-1-specific siRNA to knockdown the corresponding gene expression enhance the cell death effect of 20 dynes/cm2 shear force stimulation more in human MG63 osteosarcoma cells." (PMID 32630668, 2020). "In “Myeloid”, differentially expressed NRs such as NR4A2, NR4A1, NR3C1, RXRA, NR1D2, PPARD, and RARA were identified among metastasis, primary, and recurrent osteosarcoma tissues." (PMID 35965537, 2022). "It was shown that 20 dynes/cm2 shear force significantly induces PPARδ and PPARγ protein expressions after 4, 8 and 24 h of stimulations in human MG63 osteosarcoma cells compared to the untreated controls." (PMID 32630668, 2020). "Moreover, gene knockdown of PPARδ and SCD-1 in human MG63 osteosarcoma cells attenuated the differentiation inhibition and resulted in much more cell death of high shear force initiation." (PMID 32630668, 2020). "Interestingly, gene knockdown of PPARδ or SCD-1 seemed to partially increases the endogenous Runx2 and OCN mRNA expressions in MG63 osteosarcoma cells." (PMID 32630668, 2020). "A SCD-1 upregulation in human MG63 osteosarcoma cells under 20, but not 2, dynes/cm2 shear force stimulation was shown, and this induction was regulated by Smad1/5 and peroxisome proliferator-activated receptor δ (PPARδ) signaling." (PMID 32630668, 2020). "Moreover, cells transfected with PPARδ- or SCD-1-specific siRNA to knockdown the corresponding gene expression significantly recovered the inhibitory effect of 20 dynes/cm2 shear force on Runx2 and OCN mRNA expressions in human MG63 osteosarcoma cells." (PMID 32630668, 2020).
osteosarcoma (continued). "However, in the present results, only PPARδ and PPARγ, but not PPARα, expressions were increased in MG63 osteosarcoma cells in response to high shear force stimulation, and further results found that only PPARδ is involved in mediating SCD-1 upregulation of high shear force stimulation." (PMID 32630668, 2020).
polyp (3 papers, 2006 to 2008). A usually exophytic mass attached to the underlying tissue by a broad base or a thin stalk. "Themost prominent effect was on polyp size; the PPARδ activator increased thenumber of polyps by >2 mm five-fold." (PMID 18528523, 2008). "As mentioned in the Introduction, PPARδ was found to be unnecessary for small intestinal polyp formation, but PPARδ attenuated polyp formation in chemical and genetic models." (PMID 16969348, 2006).
sarcopenia (3 papers, 2011 to 2023). Progressive decline in muscle mass due to aging which results in decreased functional capacity of muscles. "Coincidentally, the incidence of sarcopenia (age-related muscle loss) has been shown to correlate with reduced levels of PPARδ, and pharmacological activation of PPARδ has been shown to reduce the incidence of sarcopenia by increasing nuclear accretion in myofibers." (PMID 22040534, 2011).
Arrhythmia (2 papers, 2021 to 2023). Any cardiac rhythm other than the normal sinus rhythm. "RG and WG administration had no influence on the physiological structure and function of rats' myocardium, while it could induce arrhythmia and strengthen cardiac contractility, which could be associated with upregulated p‐CaMKII and PPARδ, downregulated SERCA2a and elevated intracellular [Ca2+]i." (PMID 38455159, 2023).
benign lipoma (2 papers, 2022). "PPARγ was found to be over-expressed in DDLPS by immunostaining too and PPARδ was also found highly expressed in LPS compared to lipoma." (PMID 36557266, 2022).
brain tumors (2 papers, 2022 to 2025). "As ALD is a pediatric demyelinating disease, erucic acid would benefit myelination and reduce pediatric brain tumors since it activates transcription factor PPARδ, mediating neuroglial differentiation." (PMID 40573128, 2025).
ductal adenocarcinoma (2 papers, 2013 to 2023). "Indeed, it was shown that activation of PPARδ in the mouse mammary epithelium results in the appearance of estrogen receptor- and progesterone receptor-positive and ErbB2-negative infiltrating ductal carcinomas which are associated with an up-regulation of Plac1." (PMID 24304549, 2013). "The synthetic PPARδ agonist (GW501516) evoked rapid progression of K-RAS mutant/PPARδ+ pancreatic intraepithelial neoplasia precursor lesions to ductal adenocarcinoma in mice." (PMID 37833991, 2023).
Hypercholesterolemia (2 papers, 2020 to 2022). An increased concentration of cholesterol in the blood. "We also found altered DNA methylation in patients with hypercholesterolemia, in key genes associated with fatty acid transport and metabolism (hypomethylated: PPARD, PPARG, SLC27A1, SLC27A3 and SLC25A20, and hypermethylated: ANGPTL4, ACLS6, ACADM and CPT1A)." (PMID 33028190, 2020).
non-melanoma skin carcinoma (2 papers, 2021). "PPARδ has been shown to inhibit non-melanoma skin cancer by enhancing KC terminal differentiation and senescence, blocking KCs in the G2/M phase of the cell cycle, and inhibiting endoplasmic reticulum stress and specific inflammatory pathways." (PMID 34298981, 2021). "Thus, activation of PPARδ in KCs by specific endogenous ligands might promote tumorigenesis by upregulating oncogenic genes, increasing oxidative stress and favoring a metabolic shift toward anaerobic glycolysis, which might promote non-melanoma skin cancer." (PMID 34298981, 2021).
retinal diseases (2 papers, 2020). "Recently, a growing body of evidence suggests that PPARδ is also involved in angiogenesis, inflammation, lipid metabolism, and extracellular matrix remodeling, which are central to the pathogenesis of retinal diseases such as AMD." (PMID 33291567, 2020).
rheumatoid arthritis (2 papers, 2015 to 2021). A chronic, systemic autoimmune disorder characterized by inflammation in the synovial membranes and articular surfaces. "Additionally, PPARD is a target of sulindac, which is a cyclooxygenase inhibitor launched in clinical trials of rheumatoid arthritis or spondylitis." (PMID 33915751, 2021). "MG63 cells treated with serum from ankylosing spondylitis patients had higher PPARD, fra-1, MMP7 and OPG gene expression than did cells treated with serum from controls or rheumatoid arthritis patients (all p<0.05)." (PMID 26602520, 2015).
schizophrenia (2 papers, 2017 to 2020). A major psychotic disorder characterized by abnormalities in the perception or expression of reality. "PPARD has been suggested to contribute to the etiology of schizophrenia (SCZ) with the underlying mechanisms largely unknown." (PMID 32831816, 2020).
acute liver failure (1 paper, 2024). Rapid deterioration of liver function causing encephalopathy and coagulopathy. "The PPARδ agonist GW501516 improves survival in a mouse model of acute liver failure induced by LPS/D-GalN, primarily by suppressing the expression of pro-inflammatory cytokines such as TNF-α, IL-6, and NOS2 in vivo." (PMID 39519830, 2024).
amyotrophic lateral sclerosis (1 paper, 2026). Amyotrophic lateral sclerosis (ALS) is a neurodegenerative disease characterized by progressive muscular paralysis reflecting degeneration of motor neurons in the primary motor cortex, corticospinal tracts, brainstem and spinal cord. "Peroxisome-proliferator-activated receptor delta (PPARδ) regulates metabolic, mitochondrial, and inflammatory pathways implicated in neurodegeneration, making it an attractive therapeutic target for amyotrophic lateral sclerosis (ALS)." (PMID 41751955, 2026).
anaemia (1 paper, 2021). "Although limited sample measurements of PFOS, PFOA, TG, and FA were performed due to anaemia during pregnancy, interactions between PFOS levels and the PPARGC1A or PPARD genotype affecting FA levels were observed in the original data." (PMID 33976266, 2021).
ankylosing spondylitis (1 paper, 2015). An autoimmune chronic inflammatory disorder characterized by inflammation in the vertebral joints of the spine and sacroiliac joints. ": Serum from ankylosing spondylitis patients increases PPARD, fra-1, MMP7, OPG and RANKL expression and the OPG/RANKL ratio in MG63 cells; these effects may be due to the stimulatory effect of the serum on the Wnt pathway." (PMID 26602520, 2015).
breast adenocarcinoma (1 paper, 2016). "High PPARδ protein levels in rat breast adenocarcinomas were found to be associated with increased growth in soft agar and mice." (PMID 27270614, 2016).
Cholestatic liver disease (1 paper, 2025). "Another important cell type in cholestatic liver disease is the cholangiocyte, but the direct effect of PPARD on cholangiocytes is not known." (PMID 41180305, 2025).
colorectal adenoma (1 paper, 2006). An adenoma that arises from the colon or rectum. "It has been reported that a polymorphism in PPARδ modifies the protective effects of nonsteroidal anti-inflammatory drugs on colorectal adenomas, but other investigators have not reached the same conclusions in the context of CRC." (PMID 16969348, 2006).